ENSG00000293681 (novel transcript)
Gene: Long non-coding RNA gene on chromosome 12 (53,962,308 to 53,985,549, reverse strand). Ensembl gene ENSG00000293681.
Gene Ontology:
Biological process: heterochromatin formation